HTR1D (5-hydroxytryptamine receptor 1D)
Description:
G protein-coupled receptor for 5-hydroxytryptamine (serotonin). Also functions as a receptor for ergot alkaloid derivatives, various anxiolytic and antidepressant drugs and other psychoactive substances. Ligand binding causes a conformation change that triggers signaling via guanine nucleotide-binding proteins (G proteins) and modulates the activity of downstream effectors, such as adenylate cyclase. HTR1D is coupled to G(i)/G(o) G alpha proteins and mediates inhibitory neurotransmission by inhibiting adenylate cyclase activity. Regulates the release of 5-hydroxytryptamine in the brain, and thereby affects neural activity. May also play a role in regulating the release of other neurotransmitters. May play a role in vasoconstriction.
Synonyms: 5-HT1D; HTR1DA; HTRL; RDC4; HT1DA
Tractability: Small molecule: an approved drug acts on it; a structure with a bound ligand is known; a high-quality ligand is known; it belongs to a druggable protein family. Antibody: UniProt places it where antibodies can reach, with high confidence; its Gene Ontology location is reachable by antibodies, with high confidence; UniProt predicts a signal peptide or a membrane-spanning region. PROTAC: ubiquitination databases record sites on it; a small molecule that binds it is known.
Target class: Monoamine receptor; Family A G protein-coupled receptor; Small molecule receptor (family A GPCR); Serotonin receptor; Membrane receptor
Chemical probes: SB-714786 (high quality)
Gene: Protein-coding gene on chromosome 1 (23,190,178 to 23,217,547, reverse strand). Ensembl gene ENSG00000179546.
Subcellular location: Cell membrane
Pathways (Reactome):
Signal Transduction: G alpha (i) signalling events; Serotonin receptors
Gene Ontology:
Molecular function: G protein-coupled serotonin receptor activity; Gi/o-coupled serotonin receptor activity; protein binding; neurotransmitter receptor activity; G protein-coupled receptor activity
Biological process: adenylate cyclase-inhibiting G protein-coupled receptor signaling pathway; adenylate cyclase-inhibiting serotonin receptor signaling pathway; intestine smooth muscle contraction; chemical synaptic transmission; G protein-coupled receptor signaling pathway, coupled to cyclic nucleotide second messenger; G protein-coupled receptor signaling pathway; regulation of behavior; regulation of locomotion; smooth muscle contraction; vasoconstriction
Cellular component: plasma membrane; dendrite; membrane; synapse
Genetic constraint (gnomAD): Loss-of-function variants: 18 observed, 22.05 expected, observed/expected ratio (o/e) 0.82, 90% interval 0.56 to 1.21. The upper end of that interval is the gene's LOEUF score, 1.21, which puts it in group 5 of 6, group 1 being the genes least tolerant of losing a copy. Missense variants: 456 observed, 504.09 expected, observed/expected ratio (o/e) 0.9, 90% interval 0.84 to 0.98. Synonymous variants: 196 observed, 216.42 expected, observed/expected ratio (o/e) 0.91, 90% interval 0.81 to 1.02.
Homologues: Orthologues: chimpanzee HTR1D (99% identical), macaque HTR1D (97% identical), tropical clawed frog htr1d (73% identical), zebrafish htr1d (69% identical), Caenorhabditis elegans ser-4 (37% identical). Paralogues in human: HTR1A (41% identical), DRD1 (31% identical), DRD3 (31% identical), HRH1 (29% identical), DRD5 (29% identical), HRH2 (28% identical), HTR4 (28% identical), DRD4 (27% identical), CHRM5 (26% identical), CHRM4 (26% identical), TAAR1 (26% identical), CHRM3 (25% identical), and 13 more.
Diseases named in the same sentence as HTR1D in open-access papers:
HTR1D is named in the same sentence as 27 diseases in open-access papers, as found by Europe PMC text mining. Sharing a sentence is not in itself a finding about the gene and the disease. The quoted sentences say what the papers report.
pancreatic cancer (5 papers, 2021 to 2024). "For the sake of further exploring the specific underlying mechanism of HTR1D in pancreatic cancer, we used qPCR to detect the mRNA expression level of HTR1D in different PCs." (PMID 35813473, 2022). "Studies have indicated that HTR1D plays a role in the promotion of cell growth by serotonin in human small-cell lung cancer and contributes to the aggressive nature of pancreatic cancer, which supports our findings." (PMID 39766808, 2024). "The results showed that HTR1D, highly expressed in pancreatic cancer, was a significant indicator of patient survival." (PMID 35813473, 2022). "Other ncRNAs involved in the regulation of HTR1D in the development of pancreatic cancer still need to be further explored." (PMID 35813473, 2022). "It is demonstrated that HOXA10-AS/miR-340-3p/HTR1D ceRNA axis promotes the adverse outcome of pancreatic cancer through the PI3K-AKT signaling pathway." (PMID 36522691, 2022). "To deeply understand the function of HTR1D in pancreatic cancer in detail, we also performed a series of in vitro and in vivo experiments." (PMID 35813473, 2022). "The results illustrated that HTR1D was expressed at a high level in pancreatic cancer tissues compared to that in the normal pancreatic tissues." (PMID 35813473, 2022). "We found that HOXA10-AS was upregulated and correlated with the miR-340-3p/HTR1D axis in pancreatic cancer, as well as had a significant impact on patient survival." (PMID 35813473, 2022). "In short, here we found that miR-340-3p inhibited the progression of pancreatic cancer by degrading HTR1D." (PMID 35813473, 2022). "In summary, although this work initially substantiated that the lncRNA HOXA10-AS/miR-340-3p/HTR1D axis was involved in the occurrence of pancreatic cancer, more direct evidence was still needed to further confirm our conjecture." (PMID 35813473, 2022). "A recent study showed that miR-340-3p regulated by lncRNA HOXA10-AS could down-regulate HTR1D and inhibit the malignant biological behavior of pancreatic cancer through PI3K-Akt signaling pathway." (PMID 36572856, 2022). "We have proven that HOXA10-AS/miR-340-3p/HTR1D axis can regulate the progression of pancreatic cancer, but it is still unclear whether the key molecule HTR1D affects the PI3K-AKT signaling pathway directly or indirectly, so more mechanistic studies are needed." (PMID 35813473, 2022). "Elevated miR-340-3p blocked the progression of pancreatic cancer by downregulating HTR1D." (PMID 35813473, 2022). "All in all, we found that lncRNA HOXA10-AS could function as a ceRNA to sponge miR-340-3p to regulate HTR1D, which promoted the progression of pancreatic cancer." (PMID 35813473, 2022). "In summary, HTR1D could affect the proliferation, migration and apoptosis of pancreatic cancer partly via the PI3K-AKT signaling pathway." (PMID 35813473, 2022). "Here, our present study demonstrated that the expression level of HTR1D, positively correlated with the level of lncRNA HOXA10-AS and negatively associated with the level of miR-340-3p, was significantly increased in pancreatic cancer cell lines (PCs) compared with that in normal HPDE6-C7 cells." (PMID 35813473, 2022). "Even though we reported the involvement of HOXA10-AS/miR-340-3p/HTR1D axis in the ceRNA network of this study, this phenomenon didn't mean that there were no other ncRNAs participating in the regulation of HTR1D and thus affected the progression of pancreatic cancer." (PMID 35813473, 2022). "Therefore, exploring the role of HTR1D in pancreatic cancer may provide a novel molecular therapeutic target." (PMID 35813473, 2022).
breast carcinoma (2 papers, 2023 to 2024). "Our validation experiment in vitro showed that HTR1D knockdown inhibited the metastasis and proliferation of breast cancer cells, which also confirmed part of our analysis." (PMID 39766808, 2024). "In this study, we verified the role of HTR1D in breast cancer cells, which supports our analysis; additional in vivo and in vitro testing is required to confirm our findings." (PMID 39766808, 2024). "The genetic alteration of HTR1D, HTR3A, HTR3B, and HTR6 in breast cancer patients was significantly associated with shorter overall survival (OS)." (PMID 37795441, 2023). "Furthermore, we validated results in breast cancer and found knockdown of HTR1D inhibited breast cancer cell growth and metastasis." (PMID 39766808, 2024).
epilepsy (2 papers, 2017 to 2025). A brain disorder characterized by episodes of abnormally increased neuronal discharge resulting in transient episodes of sensory or motor neurological dysfunction, or psychic dysfunction. "MR analyses of epilepsy with FinnGen data, mainly using the methods of Wald radio and IVW, genetically predicted lower levels of HTR5A and HTR1D were associated with an increased risk of epilepsy and FE, respectively." (PMID 40170563, 2025).
migraine (2 papers, 2024). "Htr1b and Htr1d agonists, like triptans, are effective in treating migraine." (PMID 39569210, 2024).
Anorexia (1 paper, 2012). Lack of desire to eat (loss of appetite). "Polymorphisms around human HTR1D (serotonin receptor 1D) are associated with adult height and, suggestively, appetite control and anorexia, which may all be relevant to BW." (PMID 22859963, 2012).
Anxiety (1 paper, 2017). Intense feelings of nervousness, tension, or panic often arise in response to interpersonal stresses. "Htr1d affects locomotion and anxiety and also induces vascular vasoconstriction in the brain." (PMID 28337123, 2017).
basal cell carcinoma (1 paper, 2021). A carcinoma involving the basal cells.
breast invasive carcinoma (1 paper, 2024). "HTR1D/2C expressed higher levels in breast invasive carcinoma (BRCA), colon adenocarcinoma, and liver hepatocellular carcinoma." (PMID 39766808, 2024).
depression (1 paper, 2025). "Focusing on the serotonergic system—the foundation of the monoamine hypothesis of depression—we observed a significant reduction in 5-HT levels in the PFC following FMT, along with H3K27me3-mediated transcriptional repression of key genes including Tph2, Htr1d, Htr2a, Htr3a, Htr6, and Htr7." (PMID 41041075, 2025).
ductal breast carcinoma (1 paper, 2023). "In the Cancer Genome Atlas (TCGA) breast statistics, HTR1D was found to be upregulated in intraductal cribriform breast adenocarcinoma (FC = 2.373), while HTR1E level was increased in mixed lobular and ductal breast carcinoma (FC = 2.082)." (PMID 37795441, 2023).
endometriosis (1 paper, 2023). The growth of functional endometrial tissue in anatomic sites outside the uterine body. "Differential expression analysis resulted in two enhancers which were significantly differentially expressed between endometriosis cases and controls following correction for multiple testing (FDR adjusted p-value < 0.05) located in the intergenic region nearby to the genes LINC02547 and HTR1D." (PMID 37443771, 2023).
glioblastoma (1 paper, 2024). The most malignant astrocytic tumor (WHO grade IV). "The high expression of HTR1D and HTR2C was negatively related to the OS of HNSC, and almost all the HTGPCR genes, except HTR1B and HTR4, were related to the prognosis of glioblastoma." (PMID 39766808, 2024).
glioma (1 paper, 2025). A benign or malignant brain and spinal cord tumor that arises from glial cells (astrocytes, oligodendrocytes, ependymal cells). "Consequently, HTR1D may be an important molecule in the neuron-glia synapses involved by intratumoral bacteria of glioma." (PMID 39660865, 2025).
lung squamous cell carcinoma (1 paper, 2024). "Detailed examination showed that HTR1D was particularly overexpressed in liver hepatocellular carcinoma (LIHC) and HTR2C showed a similar pattern in lung squamous cell carcinoma (LUSC)." (PMID 39766808, 2024).
triple-negative breast carcinoma (1 paper, 2023). An invasive breast carcinoma which is negative for expression of estrogen receptor (ER), progesterone receptor (PR), and human epidermal growth factor receptor 2 (HER2). "With regard to triple-negative breast cancer (TNBC), the transcript levels of HTR1D/2C/6 were increased, HTR1F/2A/2B/4 expressions were decreased, and HTR1E/3A/3C/7 levels were unchanged." (PMID 37795441, 2023).
cancer (8 papers, 2021 to 2024). A tumor composed of atypical neoplastic, often pleomorphic cells that invade other tissues. "Specifically, HTR1D showed elevated levels in LIHC, LUAD, LUSC, and PAAD, with its increased expression associated with lower overall survival, suggesting that HTR1D may function as an oncogenic factor in various cancers." (PMID 39766808, 2024). "In cancer cells, overexpression of HTR1D is associated with Wnt signaling." (PMID 34919051, 2021). "The expression level of HTGPCRs in different tumors showed the specificity of genes and tumors, for example, HTR1B and HTR2B were lowly expressed in most cancers while HTR1D and HTR7 were highly expressed in most cancers." (PMID 39766808, 2024). "Lessened level of lncRNA HOXA10-AS reduced the sponging of miR-340-3p, resulting in an increase of miR-340-3p and a subsequent decrease of HTR1D to ultimately suppress the malignant biological behaviors of cancer." (PMID 35813473, 2022). "Additionally, there is rarely evidence for the function of HTR1D in cancer." (PMID 39766808, 2024). "Our research revealed that HTR1D, HTR2B, and HTR7 were highly expressed in pan-cancer." (PMID 39766808, 2024). "In addition to the C3, for these genes (CXCL8, CX3CR1, GRM8, HTR1B, HTR1D, PTGER3, SSTR1 and SUCNR1) were related to survival in the ACC and it was also could be useful in other cancers 24-31." (PMID 34220331, 2021).
tumor (3 papers, 2021 to 2025). "This is possibly due to the tumor-promoting roles of other serotonin receptors, such as HTR1D 42 and HTR7 43, that are slightly upregulated in OC and can activate the SRC signaling." (PMID 34093864, 2021). "Moreover, we identify a novel signaling axis through which NMS may downregulate HTR1D expression and subsequently inhibits the cAMP/PKA/IκBα/NF-κB pathway, ultimately suppressing tumor proliferation and promoting apoptosis." (PMID 41368641, 2025).
psychiatric disorder (1 paper, 2010). A disorder characterized by behavioral and/or psychological abnormalities, often accompanied by physical symptoms. "Htr1d has been linked with a number of psychiatric disorders." (PMID 20187946, 2010).
HTR1D also shares sentences with these, for which no sentence is quoted: small cell lung carcinoma (2 papers); colon adenocarcinoma (1); colorectal (1); colorectal cancer (1); diabetes (1); hepatocellular carcinoma (1); mood disorder (1); osteosarcoma (1); schizophrenia (1).